IGF2 (insulin like growth factor 2)
Diseases named in the same sentence as IGF2 in open-access papers (continued):
Sharing a sentence is not in itself a finding about the gene and the disease.
cardiovascular disease (15 papers, 2013 to 2024). "Prenatal Pb exposure is also associated with changes in DNA methylation in the imprinted gene IGF2, which have also been implicated in cardiovascular disease." (PMID 36325489, 2022). "The IGF system has an important role in cardiac growth during pregnancy and it is established that there is a link between the low birth weight and an increase IGF-2 gene expression in the heart that leads to an increased risk of cardiovascular disease in later life." (PMID 32745152, 2020). "Also, studies on the fetal left ventricle have shown that an elevation of IGF-2 gene expression levels and its receptor can increase the risk of cardiovascular disease in adulthood." (PMID 32745152, 2020). "Variation in IGF2 methylation could potentially serve as a mediator between adult cardiovascular disease (CVD) risk and preterm birth at VLBW." (PMID 23840686, 2013). "The interruption of IGF2 promoter regulation is a common feature of human cardiovascular diseases, which indicates that frequent deletion of biallelic IGF2 expression due to the deletion of P1 activation can be used as a diagnostic or observational marker for human cardiovascular diseases." (PMID 37063954, 2023). "Different from the high expression of IGF-2 in cardiovascular diseases, and IGF2R also has low expression in cardiovascular diseases." (PMID 37063954, 2023). "Prenatal phthalate exposure has also been associated with sex-specific dysregulation of DNA methylation and expression of the imprinted genes H19 and IGF2, both of which have important roles in cardiovascular disease and development." (PMID 36325489, 2022). "Detailed analyses revealed changes in methylation patterns within promoter regions of genes that are related to metabolic and cardiovascular disorders (IGF2, GNASAS, IL10, LEP, ABCA1, INS-IGF2, and MEG3), and these changes were associated with prenatal malnutrition." (PMID 30050001, 2018).
neurodegenerative disease (13 papers, 2013 to 2025). A disorder of the central nervous system characterized by gradual and progressive loss of neural tissue and neurologic function. "Studies on mice and cell models derived from mice have shown that the misregulation of Igf2 is associated with autistic behavior and neurodegenerative diseases, such as Huntington’s disease and Charcot’s disease." (PMID 35741015, 2022). "Insulin-like growth factor 2 (IGF2) is a secreted factor with neuroprotective properties in several neurodegenerative disease models." (PMID 40146621, 2025). "Since previous studies have shown IGF2 is beneficial for several neurodegenerative diseases, which all display aggregates of disease-causing proteins, our study may provide an insight of advanced mechanisms toward the neuroprotective effects of IGF2 in these diseases." (PMID 40713750, 2025). "In these two neurodegenerative diseases, Igf2 stimulation has a positive effect by preventing the degeneration of motor neurons and promoting their regeneration." (PMID 35741015, 2022). "All these findings suggest IGF2 as a promising target for clinical use in the treatment of neurodegenerative diseases." (PMID 32877466, 2020). "Increasing evidence suggests that IGF2 may play neurotrophic and neuroprotective roles in various neurodegenerative diseases." (PMID 38229119, 2024). "Regarding the recently discovered importance of the IGF2:IGF2R interactions in the central nervous system, our new method could find applications in the development of IGF2 analogs, which could be clinically important in the treatment of some neurodegenerative diseases." (PMID 32877466, 2020). "Analogs of IGF2, with selective binding to IGF2R and suppressed affinity for “mitogenic” IGF1R and IR-A, could be important in the treatment of neurodegenerative diseases." (PMID 32877466, 2020).
psychiatric disorder (11 papers, 2017 to 2025). A disorder characterized by behavioral and/or psychological abnormalities, often accompanied by physical symptoms. "We then examined methylation in a shortlist of genes that were previously associated with early life stress and psychiatric disorders as well as placental functioning: Ank3, Avp, Avpr1a, Avpr1b, Bdnf, Cacna1c, Cyp11b1, Cyp11b2, Fkbp5, Hsd11b1, Igf2, Morc1, Nr3c1, Oxt, Oxtr, Pclo, Slc6a4." (PMID 30655507, 2019). "Therefore, loss of the enhancer at Igf2 in mice disrupts synaptic proteins involved in neurotransmission and associated with psychiatric disease." (PMID 31053723, 2019). "In this context, recent evidence displays insulin-like growth factor 2 (IGF2)as a critical target for psychiatric diseases by playing a pivotal role in neurogenesis and in the antidepressant responses of the most widely used classical antidepressant drugs." (PMID 31554266, 2019). "In light of the findings above, we repeated the ARCL model to examine the extent to which the association of IGF2 DNA methylation was specific to ADHD symptoms as opposed to other psychiatric disorders (ODD, GAD, and MDD) for EOP versus low CP youth." (PMID 27535767, 2017). "From our perspective, the study of IGF-2 is interesting in the context of psychiatric disorders because IGF-2 can trigger IGF-1R signaling, as well as IGF-2R signaling, whereby IGF-2 binding may act as a memory enhancer and a pro-cognitive agent through the induction of neurogenesis." (PMID 37894932, 2023). "Conversely, several studies in mice have suggested that the deregulation of Igf2 expression may contribute to certain mental illnesses, leading to the hypothesis of a link between decreases in hippocampal Igf-II levels and increases in anxious and depressive behaviors." (PMID 35741015, 2022). "The purpose of this study was to assess whether the alterations in IGF-2 and IGFBP-7 in SZ patients are intrinsically related to the psychiatric disorder itself or are a secondary phenomenon due to antipsychotic treatment." (PMID 36076984, 2022).
benign tumors (8 papers, 2013 to 2025). "In the present cohort, we found that the expression of IGF2 was 20-fold higher in ACC than in ACA, which confirms that IGF2 is the most differentially expressed gene between malignant and benign tumors." (PMID 25089899, 2014). "Since IGF-2 dysregulation has been already shown in childhood and adult malignancies, as well as in benign tumors, it seemed reasonable to investigate the involvement of the IGF-2/IGF-1R pathway in primary pterygium, a benign tumor with premalignant features." (PMID 36901760, 2023).
neurodevelopmental disorder (6 papers, 2018 to 2025). A behavioral and cognitive disorder with onset during the developmental period that involves impaired or aberrant development of intellectual, motor, or social functions. "As previous studies provide evidence that IGF-2 is effective in rescuing social deficits occurring in mice models of neurodevelopmental disorders, we sought to test the effectiveness of IGF-2 in treating social deficits of the NLG3–/y mice, a monogenic model of ASDs." (PMID 38298376, 2023). "Although the changes were not significant, we observed minor changes in the growth factors, M-SCF, IGFBP-6, IGFBP-2, IGF-2 and PDGF-AA in ZIKV infected astrocytes, which may contribute to ZIKV associated neurodevelopmental disorders." (PMID 30735502, 2019).
neurological disorders (5 papers, 2020 to 2024). "Recent data from human and animal studies show that deregulation of IGF2 may increase the susceptibility to multiple diseases, including psychiatric and neurological disorder." (PMID 35178127, 2022). "The assay will be helpful for the characterization of new IGF2 mutants to study the functions of IGF2R and the development of new compounds for the treatment of neurological disorders." (PMID 32877466, 2020).
adenocarcinoma (4 papers, 2006 to 2019). A common cancer characterized by the presence of malignant glandular cells. "Conversely, IGF2BP1 and IGFBP2 expressions significantly correlated with IGF-1 and IGF-2 expressions and adenocarcinoma incidence (p < 0.05)." (PMID 31480481, 2019). "The incidence of IGF2 LOI in adenocarcinoma (62%) appears high as compared with other adenocarcinoma-specific gene alterations." (PMID 25364428, 2014). "In this context, the effect of IGF2 overexpression appears comparable with the effect of other gene alterations specific to adenocarcinoma." (PMID 25364428, 2014). "The IGF-1R and its ligands, mainly IGF-1 and IGF-2, have been suggested to play pivotal roles in proliferation, survival and migration of adenocarcinoma cells of the colon/rectum." (PMID 22159423, 2012).
endocrine disorder (4 papers, 2016 to 2023). "The IGF2 concentration in CSF is apparently regulated independently of circulating IGF2 levels: in patients with endocrine disorders that result in either constitutively high‐ or low‐serum IGFs, CSF levels of both IGFs remain normal." (PMID 36971212, 2023).
genetic disease (3 papers, 2019 to 2025). "In short, we achieved effective IGF2 SNP editing by using the combined sgRNA-shRNA/StCas9 strategy, which will facilitate the further production of base-edited animals and perhaps extend for the gene therapy for the base correction of some genetic diseases." (PMID 31057603, 2019).
cardiac disease (2 papers, 2021 to 2022). "Mice with targeted expression of an Igf2 transgene in smooth muscle cells showed enlarged hearts and shortened lifespan, which was discussed as potentially relevant to the progression of human cardiac diseases." (PMID 34360218, 2021).
kidney diseases (2 papers, 2012 to 2022). "Disruption of IGF2 has been proven to be related to different types of kidney diseases." (PMID 35596061, 2022).
animal diseases (1 paper, 2019). "Moreover, there have been so many SNP sites found in livestock, and most of them are related to animal diseases or the production traits, such as the 3072 G > A in the porcine IGF2 gene in this study." (PMID 31057603, 2019).
gastrointestinal disease (1 paper, 2023). A disease that occurs in the gastrointestinal system, excluding the hepatobiliary system. "For gastrointestinal diseases, a gelatin methacrylate/oxidized hyaluronic acid/galactosylated chitosan/Fe(III)@TA@IGF-2 200 hydrogel, loaded with insulin-like growth factor 2 (IGF-2), can regenerate the damaged hepatocytes and improve the survival of the damaged human hepatic stellate LX2 cells." (PMID 37102889, 2023).
mitochondrial disease (1 paper, 2019). "Additionally, new potentially pathogenic variants were discovered for two disorders, including IGF2/INS-IGF2 in mitochondrial disease and FBN3 in Klippel–Trenaunay–Weber syndrome." (PMID 31852928, 2019).
movement disorder (1 paper, 2019). Neurological conditions resulting in abnormal voluntary or involuntary movement, which may impact the speed, fluency, quality and ease of movement. "The top disease pathways enriched in striatal synaptosomes of mice lacking the enhancer at Igf2 were related to psychiatric, mental, and movement disorders (q < 0.05; hypergeometric test; 8 pathways of 715 tested for genes with q < 0.01)." (PMID 31053723, 2019).
myopathy (1 paper, 2022). A disease of the muscle in which the muscle fibers do not function properly. "Multiple factors contribute to steroid induced myopathy, one of which is the change in metabolism of skeletal muscle protein by transcriptional and growth factor (myostatine, Insulin-like growth factor 2 (IGF-2)) modification." (PMID 37483534, 2022).
IGF2 also shares sentences with these, for which no sentence is quoted: esophageal adenocarcinoma (6 papers); mesothelioma (6); prostate (6); polycystic ovary syndrome (5); fibrosis (4); gastrointestinal stromal tumor (4); paraganglioma (4); anxiety disorder (3); bacterial infections (3); brain disorder (3); colon adenocarcinoma (3); dementia (3); Lynch syndrome (3); malignant pheochromocytoma (3); multiple endocrine neoplasia type 1 (3); neural tube defect (3); placental insufficiency (3); systemic sclerosis (3); triple-negative breast carcinoma (3); Arthritis (2); asthma (2); Atrophy (2); Barrett esophagus (2); cervical intraepithelial neoplasia (2); choriocarcinoma (2); chronic hepatitis (2); coronary artery disease (2); eating disorder (2); Fanconi anemia (2); Hemihypertrophy (2).
A further 165 diseases each share a sentence with IGF2 in 2 papers or fewer.